GSDME (gasdermin E)
Description:
[Gasdermin-E]: Precursor of a pore-forming protein that converts non-inflammatory apoptosis to pyroptosis. This form constitutes the precursor of the pore-forming protein: upon cleavage, the released N-terminal moiety (Gasdermin-E, N-terminal) binds to membranes and forms pores, triggering pyroptosis. [Gasdermin-E, N-terminal]: Pore-forming protein produced by cleavage by CASP3 or granzyme B (GZMB), which converts non-inflammatory apoptosis to pyroptosis or promotes granzyme-mediated pyroptosis, respectively. After cleavage, moves to the plasma membrane, homooligomerizes within the membrane and forms pores of 10-15 nanometers (nm) of inner diameter, allowing the release of mature interleukins (IL1B and IL16) and triggering pyroptosis. Binds to inner leaflet lipids, bisphosphorylated phosphatidylinositols, such as phosphatidylinositol (4,5)-bisphosphate. Cleavage by CASP3 switches CASP3-mediated apoptosis induced by TNF or danger signals, such as chemotherapy drugs, to pyroptosis. Mediates secondary necrosis downstream of the mitochondrial apoptotic pathway and CASP3 activation as well as in response to viral agents. Exhibits bactericidal activity. Cleavage by GZMB promotes tumor suppressor activity by triggering robust anti-tumor immunity. Suppresses tumors by mediating granzyme-mediated pyroptosis in target cells of natural killer (NK) cells: cleavage by granzyme B (GZMB), delivered to target cells from NK-cells, triggers pyroptosis of tumor cells and tumor suppression. [Gasdermin-E, N-terminal]: (Microbial infection) Pore-forming protein, which promotes maternal placental pyroptosis in response to Zika virus infection, contributing to adverse fetal outcomes.
Synonyms: ICERE-1; DFNA5
Tractability: Antibody: UniProt places it where antibodies can reach, with high confidence; its Gene Ontology location is reachable by antibodies, with high confidence. PROTAC: UniProt records ubiquitination sites on it; ubiquitination databases record sites on it.
Gene: Protein-coding gene on chromosome 7 (24,698,355 to 24,757,940, reverse strand). Ensembl gene ENSG00000105928.
Subcellular location: Cell membrane (Gasdermin-E, N-terminal); Cytoplasm, cytosol (Gasdermin-E)
Subcellular location (Human Protein Atlas): Cytosol
Pathways (Reactome):
Programmed Cell Death: Pyroptosis; Release of apoptotic factors from the mitochondria
Disease: Defective pyroptosis
Immune System: Regulation of TLR by endogenous ligand
Gene Ontology:
Molecular function: cardiolipin binding; phosphatidylinositol-4,5-bisphosphate binding; protein binding; wide pore channel activity
Biological process: cellular response to tumor necrosis factor; cellular response to virus; negative regulation of cell population proliferation; positive regulation of intrinsic apoptotic signaling pathway; positive regulation of MAPK cascade; programmed cell death; pyroptotic inflammatory response; sensory perception of sound; transmembrane transport
Cellular component: cytosol; membrane; plasma membrane; cytoplasm
Genetic constraint (gnomAD): Loss-of-function variants: 43 observed, 48.58 expected, observed/expected ratio (o/e) 0.89, 90% interval 0.69 to 1.14. The upper end of that interval is the gene's LOEUF score, 1.14, which puts it in group 5 of 6, group 1 being the genes least tolerant of losing a copy. Missense variants: 648 observed, 621.46 expected, observed/expected ratio (o/e) 1.04, 90% interval 0.98 to 1.11. Synonymous variants: 256 observed, 262.59 expected, observed/expected ratio (o/e) 0.97, 90% interval 0.88 to 1.08.
Gene-disease validity (ClinGen):
ClinGen rates the evidence that GSDME causes each of these diseases.
nonsyndromic genetic hearing loss (autosomal dominant): Definitive.
Homologues: Orthologues: chimpanzee GSDME (99% identical), macaque GSDME (95% identical), dog GSDME (79% identical), guinea pig GSDME (76% identical), rat Gsdme (72% identical), mouse Gsdme (72% identical), pig GSDME (72% identical), rabbit GSDME (62% identical), tropical clawed frog gsdme (43% identical), zebrafish gsdmeb (34% identical), zebrafish gsdmea (26% identical).
Diseases named in the same sentence as GSDME in open-access papers:
GSDME is named in the same sentence as 201 diseases in open-access papers, as found by Europe PMC text mining. Sharing a sentence is not in itself a finding about the gene and the disease. The quoted sentences say what the papers report.
melanoma (107 papers, 2017 to 2025). A malignant, usually aggressive tumor composed of atypical, neoplastic melanocytes. "In GSDME-deficient melanoma, targeted inhibitors fail to promote cleavage of GSDME and release of HMGB1, leading to a reduction in the infiltration of activated dendritic cells (DCs) and tumour-associated T cells." (PMID 38906860, 2024). "Decitabine up-regulates the expression of GSDME by inhibiting DNA methylation, and then causes pyroptosis of cancer cells and induces anti-tumor immunity of melanoma and TNBC." (PMID 38654314, 2024). "Studies have shown that melanoma cells deficient in GSDME-mediated pyroptosis fail to mount a durable anti-tumor immune response to BRAFi + MEKi treatment." (PMID 37373523, 2023). "Mechanistically, BRAFis + MEKis treatment activates caspase-3/GSDME signaling pathways, leading to tumor-associated T cells infiltration and activating dendritic cells to kill melanoma cells." (PMID 38104141, 2023). "Loss of GSDME facilitates the resistance of melanoma cell lines to etoposide, which can be rescued by overexpression of GSDME." (PMID 36920176, 2023). "GSDME-deficient melanoma showed defective HMGB1 release, decreased tumor-associated T cells, and activated DC infiltrates in response to BRAFi + MEKi, and more frequent tumor regrowth was observed after drug removal." (PMID 35739593, 2022). "GSDME was considered as a tumor suppressor gene; for example, decreased expression of GSDME mRNA is associated with increased etoposide resistance in melanoma cells." (PMID 36497244, 2022). "The combinations of BRAF inhibitors and MEK inhibitors (BRAFi + MEKi) caused durable regression of melanoma by promoting cleavage of GSDME and the release of HMGB1." (PMID 35739593, 2022). "In melanoma, low-GSDME expression has been described to cause tumor cells to be resistant to etoposide, with the activation of pyroptosis, reversing chemotherapy drug resistance." (PMID 35846123, 2022). "GSDME-deficient melanoma cells formed and grew larger tumors in vivo compared to control melanoma cells." (PMID 33634141, 2021). "Deficiency of GSDME expression showed resistance to etoposide in melanoma cell lines, but transfecting an expression vector encoding GSDME increased the sensitivity to etoposide." (PMID 34305590, 2021). "Mechanistically, gasdermin E was indispensable for melanoma cell response as GSDME deficiency resulted in more frequent tumor re-growth when administration of drugs was ceased." (PMID 32340261, 2020). "The expression level of GSDME was barely detectable or low in human breast cancer and melanoma cells, and low levels of GSDME in the cells were associated with resistance to anti-cancer therapies." (PMID 33348858, 2020). "It was found that GSDME deficient melanoma cells formed and grew larger tumors than their wild-type counterparts." (PMID 31616642, 2019). "ROS caused by iron supply can lead to pyroptosis of melanoma cells by GSDME cleavage." (PMID 38336727, 2024). "In etoposide-resistant melanoma cells, loss of GSDME decreased cell response to etoposide." (PMID 35662735, 2022). "Interestingly, GSDME‐deficient melanoma represents defective HMGB1 release, the reduced infiltration of tumor‐associated T cells and activated DCs in response to BRAFi + MEKi treatment, and the more frequent tumor regrowth after drug removal." (PMID 34459122, 2021). "However, BRAFi + MEKi treatment loses the therapeutic effect against GSDME-deficient melanoma, indicating BRAFi + MEKi treatment kills melanoma cells mainly through induction of pyroptosis." (PMID 33941231, 2021). "Consistent with its tumor suppressive role in CRC, GSDME deficiency accelerates melanoma growth." (PMID 33033617, 2020). "GSDME deficiency also accelerates cell growth in culture and in a mouse model of melanoma." (PMID 30976076, 2019).
melanoma (continued). "Additionally, the combination of BRAF and MEK inhibitors was reported to induce GSDME-dependent pyroptosis through caspase-3 and the release of pro-inflammatory factors in melanoma cells, which is associated with an increase in CD4+ T cell and CD8+ T cell infiltration and decreased TAM levels." (PMID 35990696, 2022). "Additionally, Erkes and colleagues found that combined BRAF inhibitor and MEK inhibitor treatment causes GSDME‐mediated pyroptosis in BRAFV600E/K ‐mutant melanoma via active caspase‐3, ultimately resulting in HMGB‐1 release to activate antitumor T‐cell responses." (PMID 33033617, 2020). "Moreover, loss of GSDME has been associated with resistance to etoposide in melanoma cells." (PMID 30804337, 2019). "In conclusion, these results suggest that TRI-03 primarily induces pyroptosis in melanoma cells through the activation of the caspase-9/caspase-3/GSDME signaling pathway." (PMID 40486906, 2025). "To investigate if GSDME can execute a pyroptotic program in GB cells, we used raptinal, a fast inducer of apoptosis, which recently has been shown to execute GSDME-mediated pyroptosis downstream of caspase 3 in melanoma cells." (PMID 40544161, 2025). "One such approach involves the use of the caspase-3 activator raptinal, which induces pyroptosis in BRAF-mutant melanoma through GSDME cleavage." (PMID 41235238, 2025). "For example, in melanoma cells, iron-activated ROS trigger GSDME-dependent pyroptosis via the Tom20-Bax-caspase-9-caspase-3-GSDME axis." (PMID 40424719, 2025). "TRI-03 also reduces XIAP expression via the autophagy pathway, facilitating caspase activation and resulting in irreversible GSDME-mediated pyroptosis in melanoma cells." (PMID 40486906, 2025). "Meanwhile, the combination of BRAF inhibitor and MEK inhibitor was shown to induce GSDME-dependent pyroptosis in mouse melanoma cells and increase T cell infiltration." (PMID 40645933, 2025). "Dinaciclib 70 is a selective inhibitor of cyclin-dependent kinases (CDKs), CDK1,2,5,9, used to induce pyroptosis in melanoma through caspase-1/GSDME/Bax activation." (PMID 39316325, 2025). "Another research showed that chemotherapeutic agents in gastric cancer and small-molecule kinase inhibitors in lung cancer and melanoma cells also induced pyroptosis through the GSDME/caspase-3 pathway to contribute significantly on tumor suppression." (PMID 40761801, 2025). "GSDME has demonstrated inhibitory effects on cell proliferation and tumor progression in gastric cancer (GC), melanoma, colorectal cancer (CRC), and breast cancer, where its expression is upregulated, indicating its potential role as a tumor-suppressing agent." (PMID 38304430, 2024). "Pyroptosis in melanoma cells was executed by cleavage of GSDME after activation of Caspase3 after treatment with platinum-based drugs." (PMID 39343834, 2024). "In March 2020, the GSDME-mediated pyroptosis pathway was found to inhibit the proliferation of gastric cancer, melanoma, colon cancer, and breast cancer cells by activating antitumor immunity." (PMID 39526199, 2024). "In melanoma, it has been reported that the key effector molecule of pyroptosis, GSDME, exhibits tumor-suppressive effects." (PMID 38334883, 2024). "In malignant tumors, the low expression of GSDME related to pyroptosis can make melanoma MeWo cells obtain resistance to etoposide." (PMID 38902235, 2024). "Conversely, GSDME-knockdown melanoma displayed defective DAMP release and reduced intratumoral T cell infiltration during BRAFi + MEKi treatment." (PMID 38283351, 2023). "For instance, BRAF inhibitors plus MEK inhibitors treatment can activate GSDME pyroptosis to enhance anti-tumor immunity in GSDME-expressing melanoma." (PMID 36742298, 2023). "Activated Tom20 recruited Bax to the mitochondria, which then induced further activation of caspase-3 by cytochrome C and ultimately trigger GSDME-mediated pyroptosis in melanoma cells." (PMID 37426634, 2023).
melanoma (continued). "Recent research has cast light on the crucial role of GSDME-mediated pyroptosis in treating various tumors, including melanoma, lung cancer, digestive malignancies, gynecologic malignancies, etc." (PMID 38104141, 2023). "Iron-mediated ROS elevation promoted the oxidation of the mitochondrial outer membrane protein Tom20 in melanoma cells and induced pyroptosis by activating the Bax/Caspase-3/GSDME pathway." (PMID 37679782, 2023). "Nano-CD induced endogenous GSDME expression and released cisplatin, resulting in pyroptosis in melanoma cells." (PMID 37373523, 2023). "Lage’s study found that GSDME expression elevation enhanced melanoma cells’ sensitivity to etoposide, indicating that GSDME-mediated pyroptosis contributes to melanoma etoposide resistance." (PMID 38104141, 2023). "BRAFi + MEKi, which are FDA-approved for the treatment of BRAFV600E/K-mutant melanoma, activated DCs and tumor-specific T cells in melanoma by triggering GSDME-executed pyroptosis and promoting DAMP release." (PMID 38283351, 2023). "By inducing GSDME expression in vitro, it supresses colony formation and tumor cell proliferation in gastric cancer, melanoma and colorectal cancer and reduced metastasis in breast cancer." (PMID 35795683, 2022). "The mRNA expression level of GSDME was significantly reduced in melanoma cells with 33-fold etoposide-resistant." (PMID 35462927, 2022). "Consistent with our result, high levels of GSDME have been detected in many cancers, including lung cancer, melanoma, osteosarcoma, digestive cancers, and head and neck cancer." (PMID 36457716, 2022). "It has also been indicated that targeted drugs induce GSDME-mediated cellular scorching in melanoma, linking the tumor immune microenvironment to T cell-mediated anti-tumor immunity." (PMID 35419279, 2022). "GSDME can also inhibit the proliferation of gastric cancer, melanoma, and colorectal cancer cells and the invasion of breast cancer." (PMID 35480866, 2022). "Gsdme-/- mice has been generated and deletion of GSDME in other cell types such as immortalized BMDMs, murine melanoma GSDME KO B16 cell line, and murine thymoma cell line EG70-Ova haven been reported." (PMID 35795683, 2022). "Several studies have also shown that activating compounds that activate the Caspase3-GSDME pathway is effective in cancer therapy, and GSDME has been considered one of the targets for the treatment of different cancer types (eg, melanoma, lung cancer)." (PMID 36248872, 2022). "It was shown that a combination of BRAF and MEK inhibitors treatment triggered the pyroptosis of human melanoma cells through inducing caspase-3 activation and GSDME cleavage." (PMID 35896522, 2022). "Normally, GSDME is highly expressed in normal tissues, and in certain cancer lines, such as melanoma, lung breast, colon, and esophageal cancers." (PMID 35002520, 2022). "In melanoma, Cytochrome c released from damaged mitochondria activates caspase-3 to induce GSDME-mediated pyroptosis and participate in the tumor immune response." (PMID 34887391, 2021). "A latest study demonstrated that combinations of BRAF inhibitors and MEK inhibitors (BRAFi + MEKi) treatment, a FAD-approved approach for BRAFV600E/K-mutant melanoma, induce GSDME dependent pyroptosis and enhance cytotoxic T-cell infiltration." (PMID 33941231, 2021). "In contrast to non‐tumoral tissues, expression of GSDME is limited in most cancers including gastric cancer, melanoma, CRC, invasive breast cancer, and other human cancers." (PMID 34459122, 2021). "For example, in melanoma cells, iron‐activated ROS engenders pyroptosis through the Tom20‐Bax‐caspase‐GSDME pathway." (PMID 34369076, 2021). "Subsequently, this effect leads to cytochrome C release, caspase-3 activation, and eventually GSDME-related pyroptosis in the mouse melanoma cell lines YUMM1.7 and D4M3.A and immunocompetent C57BL/6 mice." (PMID 34522213, 2021).